CYP1A1 (cytochrome P450 family 1 subfamily A member 1)
Diseases named in the same sentence as CYP1A1 in open-access papers (continued):
Sharing a sentence is not in itself a finding about the gene and the disease.
coronary artery disease (4 papers, 2014 to 2021). "The Cytochrome P450 Family 1 Subfamily A Member 1) CYP1A1 (enzyme is known to cause coronary artery disease through various mechanisms." (PMID 34316491, 2021). "This study assessed the association between human CYP1A1 gene polymorphisms and coronary artery disease (CAD) in the Uygur and Han in China." (PMID 25189712, 2014).
COVID-19 (4 papers, 2021 to 2024). A disease caused by infection with severe acute respiratory syndrome coronavirus 2. "Our study shows for the first time that Wnt5A induces the gene expression of CYP1A1 and CYP1B1 enzymes involved in phase I metabolism of a broad spectrum of drugs including chloroquine (the controversial drug for COVID-19) that is known to cause toxicity in myocardium." (PMID 34079452, 2021). "ACE (AUC: 0.923), CYP1A1 (AUC: 0.902), EME1 (AUC: 0.977), CD52 (AUC: 0.970), MYBL2 (AUC: 0.995), CDC25A (AUC: 0.998), BCL6 (AUC: 0.966) and CD3D (AUC: 0.955) showed relatively good diagnostic efficiency in distinguishing COVID-19 patients from healthy controls." (PMID 38978778, 2024).
periodontitis (4 papers, 2019 to 2023). An acute or chronic inflammatory process that affects the tissues that surround and support the teeth. "This study group demonstrated a significantly increased risk for periodontitis in individuals exhibiting the polymorphic CYP1A1 m2 allele." (PMID 35408801, 2022). "The object of another study was to investigate the roles of genetic polymorphisms of metabolizing enzymes as risk factors for periodontitis, including CYP1A1." (PMID 35408801, 2022). "In addition, we found that the expression of AhR and its downstream CYP1A1 was upregulated in gingival epithelia in periodontitis mice compared with their normal controls." (PMID 31691738, 2019). "In the present study, AhR and its direct targets CYP1A1 and CYP1B1 were reduced in P. gingivalis‐infected experimental periodontitis mice model." (PMID 36446468, 2023). "Similarly, gene expression of AhR, CYP1A1, CYP1B1, and IDO analysed by qRT‐PCR were also decreased in periodontitis mice." (PMID 36446468, 2023).
pterygium (4 papers, 2010 to 2025). A wedge-shaped fibrovascular lesion arising from the bulbar conjunctiva and extending to the cornea. "We previously reported that benzo[a]pyrene (B[a]P) 7,8-diol 9,10-epoxide (BPDE)-like DNA adducts detected in pterygium samples were associated with allelic variants of CYP1A1." (PMID 22876118, 2012). "We also found that the risk of pterygium formation was 2.339 fold greater with the CYP1A1 m2/m2 genotype as compared with the C/T and T/T genotypes." (PMID 22876118, 2012). "Subjects who were heterozygous (m1/m2) or homozygous (m2/m2) for the CYP1A1 polymorphisms appeared to experience a higher risk of pterygium than those who were homozygous for the wild-type allele (m1/m1; OR: 1.553; 95% CI: 1.07–2.290, p=0.037)." (PMID 20596254, 2010). "The analysis of the CYP1A1 MSPI polymorphisms in pterygium showed that 34 (33.0%) were homozygous for the m1/m1 genotype, 15 (14.6%) were homozygous for the m2/m2 genotype, and 54 (52.4%) were heterozygous for the m1/m2 genotype." (PMID 20700368, 2010). "In the present study, we also found that the CYP1A1 polymorphism correlated with BPDE-like DNA adduct formation in pterygium." (PMID 20700368, 2010). "Our previous study showed that BPDE-like DNA adduct levels correlate with CYP1A1 gene polymorphism in pterygium." (PMID 20596254, 2010). "The multiple logistic regression analysis showed that the CYP1A1 genotype is related to the risk of pterygium after an adjustment with GSTM1 polymorphisms." (PMID 20596254, 2010). "Our previous report indicated that BPDE-like DNA adducts were detected in pterygium samples and the DNA adduct levels were associated with the genetic polymorphisms of CYP1A1." (PMID 20596254, 2010). "Our previous report indicated that BPDE-like DNA adduct levels in pterygium were associated with CYP1A1 gene polymorphisms." (PMID 20596254, 2010). "This suggests that CYP1A1 polymorphisms are significant as risk factors in BPDE-like DNA adduct formation in pterygium patients." (PMID 20700368, 2010). "In this study, we found that CYP1A1 with the m1/m2 and m2/m2 genotype has a 1.553 fold risk for pterygium compared with the m1/m1 genotypes." (PMID 20596254, 2010). "The analysis of the CYP1A1 polymorphisms in pterygium showed that 68 (33.2%) were homozygous for the m1/m1 genotype, 29 (14.1%) were homozygous for the m2/m2 genotype, and 108 (52.7%) were heterozygous for the m1/m2 genotype." (PMID 20596254, 2010). "Our data provide evidence that the BPDE-like DNA adduct formation in pterygium samples was associated with CYP1A1 polymorphisms." (PMID 20700368, 2010). "We also found that CYP1A1 polymorphisms correlated with the BPDE-like DNA adduct formation in pterygium." (PMID 20596254, 2010). "Therefore, we suggest that CYP1A1 protein expression in pterygium tissues is associated with allelic variants." (PMID 22876118, 2012). "Therefore, in this study, we analyze the association of CYP1A1 allelic variants with protein expression using real-time PCR and immunohistochemistry methods with 150 pterygium specimens and 50 normal conjunctiva samples." (PMID 22876118, 2012). "Multiple logistic regression analysis of CYP1A1 genotype, age, sex, and risk of pterygium." (PMID 22876118, 2012). "However, in our study we found that only the CYP1A1 polymorphisms were associated with BPDE-DNA adduct formation in pterygium." (PMID 20700368, 2010). "In conclusion, a CYP1A1 polymorphism is correlated with pterygium and might become a marker for the prediction of pterygium susceptibility." (PMID 20596254, 2010). "In this study, we try to detect the BPDE-like DNA adducts, using immunohistochemistry in 103 pterygium specimens, and we compare them with CYP1A1 and GSTM1 polymorphisms to understand the relationship between environmental exposure and genetic polymorphism in pterygium." (PMID 20700368, 2010). "Our data indicated that the CYP1A1 polymorphism is a risk factor for pterygium." (PMID 20596254, 2010).
pterygium (continued). "Therefore, we sought to determine whether allelic variation of CYP1A1 is associated with protein expression and protein activity in pterygium." (PMID 22876118, 2012). "Therefore, we hypothesize that after exposure to environmental PAHs, the CYP1A1 gene polymorphism may result in high levels of BPDE-like DNA adduct formation contributing to the risk of pterygium formation." (PMID 20596254, 2010). "The CYP1A1 MspI polymorphism may be used as a risk factor for pterygium." (PMID 20596254, 2010). "CYP1A1 expression in pterygium correlates with allelic variation and can be used as an independent risk marker." (PMID 22876118, 2012). "The prevalence of pterygium in subjects with CYP1A1 protein expression appeared to be greater than the prevalence of pterygium in those without CYP1A1 protein expression (OR 11.49, 95% CI 2.60–5.0, p=0.001)." (PMID 22876118, 2012). "Immunohistochemical analysis of CYP1A1 protein expression in pterygium (n=150) and controla (n=50) tissues, p<0.0001." (PMID 22876118, 2012). "After adjustment for age and sex, multiple logistic regression analysis showed that the CYP1A1 genotype is related to pterygium." (PMID 22876118, 2012). "Our previous study showed that BPDE-like DNA adduct levels correlate with CYP1A1 allelic variation in pterygium." (PMID 22876118, 2012). "CYP1A1 protein expression was significantly greater in the pterygium group than in the control group (p<0.0001)." (PMID 22876118, 2012). "Immunohistochemistry was used to analyze CYP1A1 protein expression in 150 pterygium and 50 conjunctiva samples." (PMID 22876118, 2012). "In this study, we analyzed the PAHs metabolic enzymes, CYP1A1 and GSTM1, and their gene polymorphisms in pterygium and compared them with control groups." (PMID 20596254, 2010). "Therefore, we suggest that CYP1A1 protein expression in pterygium contributes to BPDE-like DNA adduct formation." (PMID 22876118, 2012). "CYP1A1 expression was greater in the pterygium group than in the control group (p<0.0001)." (PMID 22876118, 2012). "We compared CYP1A1 protein expression in the pterygium and control groups." (PMID 22876118, 2012). "The association of CYP1A1 protein and genetic polymorphism have been reported in several types of cancer, but no any report was discussed about this in pterygium." (PMID 22876118, 2012). "In addition, CYP1A1 protein expression in the pterygium group was significantly greater than in the control group." (PMID 22876118, 2012). "Therefore, we suggest that allelic variation of CYP1A1 contributes to protein expression in pterygium and results in high levels of BPDE-like DNA adduct formation." (PMID 22876118, 2012). "In the pterygium group, 48 (33%) samples were positive for CYP1A1 expression." (PMID 22876118, 2012). "In summary, we found that CYP1A1 protein expression in pterygium tissue was significantly greater than in nonpterygium control tissues, and CYP1A1 protein expression is associated with allelic variation." (PMID 22876118, 2012). "Forty-eight (33.3%) pterygium specimens tested positive for CYP1A1 protein expression." (PMID 22876118, 2012). "To verify whether the CYP1A1 protein activity in pterygium is associated with genetic allelic variation, we established primary cultured epithelial cell lines (PEC cells) with different CYP1A1 genotypes from the pterygium patients." (PMID 22876118, 2012). "CYP1A1 and GSTM1 polymorphisms in pterygium analyzed by PCR-RFLP and PCR." (PMID 20700368, 2010). "The effects of gender, CYP1A1, and GSTM1 polymorphisms on DNA adduct levels in pterygium patients." (PMID 20700368, 2010). "Multiple logistic regression analysis of CYP1A1 and GSTM1 genotypes and the risk of pterygium." (PMID 20596254, 2010).
pterygium (continued). "Therefore, BPDE-like DNA adducts and CYP1A1 and GSTM1 polymorphisms were detected in this study to provide more molecular evidence to understand the cause of BPDE-like DNA adduct formation in pterygium." (PMID 20700368, 2010). "Therefore, we hypothesize that after exposure to environmental PAHs, the CYP1A1 allelic variation may result in high levels of BPDE-like DNA adduct formation, contributing to the risk of pterygium." (PMID 22876118, 2012). "Therefore, allelic variants of CYP1A1 may contribute to BPDE-DNA adduct formation and pterygium progression." (PMID 22876118, 2012). "Therefore, we hypothesize that that the genetic polymorphisms of CYP1A1 and GSTM1 increase the risk of pterygium." (PMID 20596254, 2010). "Therefore, the genetic polymorphisms of CYP1A1 and GSTM1 may contribute to BPDE-like DNA adduct formation and pterygium progression." (PMID 20596254, 2010). "Therefore, genetic polymorphisms of CYP1A1 and GSTM1 may contribute to BPDE-like DNA adduct formation and pterygium progression." (PMID 20700368, 2010). "Therefore, we hypothesize that the genetic polymorphisms of CYP1A1 and GSTM1 increase the risk for pterygium." (PMID 20596254, 2010). "Genotype distribution of CYP1A1 and GSTM1 genes among pterygium patients and control group." (PMID 20596254, 2010). "The relationship between BPDE-like DNA adduct levels and CYP1A1 and GSTM1 gene polymorphisms in pterygium is not clear." (PMID 20700368, 2010).
renal cell carcinoma (4 papers, 2013 to 2024). "It is important to acknowledge that the link between CYP1A1*2C polymorphism and renal cell carcinoma was only apparent when adding smoking as a variable, suggesting that the mutated gene does not, by itself, protect from cancer, but rather may act as a preventative mechanism." (PMID 39769254, 2024). "A recent study performed by the group of Murray identified CYP1B1 activity in renal cell carcinoma using an activity assay based on the O-deethylation of 7-ethoxyresorufin and the use of the CYP1A1/CYP1B1 inhibitor α-napthoflavone." (PMID 24358191, 2013).
Stroke (4 papers, 2019 to 2025). Sudden impairment of blood flow to a part of the brain due to occlusion or rupture of an artery to the brain. "Another study found an association between CYP1A1 activity and the occurrence of stroke." (PMID 37342754, 2023). "This study aimed to observe the relationship between CYP1A1 and CYP1A2 variants and stroke risk in the Chinese population." (PMID 33046100, 2020). "The chi-square test and logistic-regression analysis were used to explore the relationship between CYP1A1 and CYP1A2 variants and stroke risk." (PMID 33046100, 2020). "This study investigated the association between CYP1A1 variants and CYP1A2 and stroke risk in the Chinese Han population." (PMID 33046100, 2020). "Then, molecular experiment is used to further verify the role of CYP1A1 and CYP1A2 polymorphisms in the course of stroke." (PMID 33046100, 2020). "In this study, the results first showed that CYP1A1 and CYP1A2 variants were associated with stroke risk." (PMID 33046100, 2020). "In the codominant model, compared with the carriers of TT genotype, subjects with TC genotype of CYP1A1 rs4646422 had a negative effect on the risk of stroke (adjusted OR = 1.69, 95% CI: 1.04–2.74, P = 0.035)." (PMID 33046100, 2020). "Moreover, the relationship between CYP1A1 rs1048943 and stroke risk was analyzed in lacunar infarction cases vs non-lacunar infarction cases adjusted for age and gender." (PMID 33046100, 2020). "In addition, we analyzed the association between CYP1A1 rs1048943 and stroke risk in cerebral infarction cases vs non-cerebral infarction cases." (PMID 33046100, 2020). "Studies have shown that ESR1 can downregulate the expression of CYP1A1 and 20-HETE after stroke." (PMID 40864781, 2025). "By comparing with non-hypertensive cases, the correlation between CYP1A1 rs4646422, CYP1A2 (rs762551 and rs2470890) and stroke risk in hypertensive cases was first analyzed in the allele model." (PMID 33046100, 2020). "Finally, the results only showed that polymorphisms of CYP1A1 and CYP1A2 were related to the risk of stroke, and there was no more clear mechanism study." (PMID 33046100, 2020). "Since AhR promotes apoptosis, controls ERα, and is highly expressed in brain tissue in experimental models of stroke, we hypothesize that anti-apoptotic action of DIM against OGD is mediated via inhibition of AhR/CYP1A1 and/or stimulation of ERα/CYP19A1 signaling pathways." (PMID 30778709, 2019). "However, the exact mechanism of CYP1A1 and CYP1A2 in stroke remains unclear." (PMID 33046100, 2020).
viral infection (4 papers, 2015 to 2023). "When analyzed with respect to the occurrence of viral infections, a positive correlation was observed with the CYP1A1 (rs2606345) A allele (β = 1,26 OR = 3.53 p value = 0.05)." (PMID 37630611, 2023). "Although the A allele of the polymorphism has been found to reduce the promoter activity of CYP1A1, a functional correlation between the polymorphism and a predisposition to viral infections requires further investigation." (PMID 37630611, 2023). "Up-regulated cyp1a1 expression is a common response to viral infection by reovirus in grass carp, Ctenopharyngodon idella." (PMID 38104092, 2023). "Key down-regulated genes (i.e., CREB5, SLC2A4, SREBF1, CYP1A1, CHARD and COMP) are related to insulin resistance, response to virus infection, AMPK signalling and ECM receptor interaction (Table A6)." (PMID 34830490, 2021).
acute lymphoblastic leukemia (3 papers, 2015 to 2024). Leukemia with an acute onset, characterized by the presence of lymphoblasts in the bone marrow and the peripheral blood. "Our study aimed to investigate the association between cytochrome P450 1A1 (CYP1A1) polymorphisms (T3801C and A2455G) and acute lymphoblastic leukemia (ALL) risk, considering genetic models and ethnicity." (PMID 38485870, 2024). "Besides genetic polymorphisms of CYP1A1, CYP2D6, GSTM1 and GSTT1 associate with acute lymphoblastic leukemia in Indian children." (PMID 28902850, 2017).
Arthritis (3 papers, 2019 to 2021). Inflammation of a joint. "We first noted an increased expression of the Ahr gene in the synovium 24h after serum injection before the appearance of clinical signs of arthritis, which likely accounts for increased expression of known AHR‐dependent target genes expression such as Il‐22 and Cyp1a1." (PMID 33734594, 2021). "Most importantly, treatment of WT mice with these AhR ligands in vivo demonstrated that 5-HIAA, but not KYNA, suppressed arthritis development and increased both Cyp1a1 and Il10 transcription in B cells ex vivo." (PMID 32213346, 2020).
atopic dermatitis (3 papers, 2021 to 2025). "Increased CYP1A1 has been detected in the inflamed skin of patients with atopic dermatitis and in the PBMCs of patients with systemic lupus erythematosus, suggesting that upregulation of the pathway during inflammation and autoimmunity may occur in an attempt to restrict immunopathology." (PMID 33385398, 2021).
brain cancer (3 papers, 2010 to 2025). A primary or metastatic malignant neoplasm affecting the brain. "The risk of developing malignant tumors in the brain during childhood is increased in carriers of a minor variant of CYP1A1 (606G)." (PMID 22649665, 2010). "Increased CYP1A1 activity, observed in human brain glioma samples, generates reactive intermediates and DNA adducts, promoting carcinogenesis and indicating a potential link between brain CYP1A1 activity and susceptibility to environmental toxin-related brain cancers." (PMID 40126262, 2025). "Furthermore, increased expression levels of CYP1A1 (activating polychlorinated biphenyls, aromatic amines, PAHs, and alkylnitrosamines) could pose a tipping issue as it is positively associated with various malignancies including brain cancer." (PMID 38333013, 2024).
Cirrhosis (3 papers, 2009 to 2025). A chronic disorder of the liver in which liver tissue becomes scarred and is partially replaced by regenerative nodules and fibrotic tissue resulting in loss of liver function. "On the contrary, the results of qPCR and Western blot analyses show a markedly reduced increase in the mRNA level and protein expression of CYP1A1 and CYP1A2 in ascitic rats, indicating that induction is greatly curtailed in decompensated cirrhosis." (PMID 23626760, 2013). "The results of our kinetic analysis are in keeping with those of qPCR and Western blot experiments, since they show that induced EROD (CYP1A1) activity is totally preserved in rats with non-ascitic cirrhosis, whereas it is markedly reduced (by about 60%) in ascitic rats." (PMID 23626760, 2013).
colorectal adenoma (3 papers, 2007 to 2020). An adenoma that arises from the colon or rectum. "Previously, SNPs in both CYP1A1 and CYP1A2 have been associated with colorectal adenomas and carcinomas, therefore the observation of some relationship between CYP1A2 rs2069522 and risk in our study is not without precedent." (PMID 17615053, 2007).
endothelial dysfunction (3 papers, 2009 to 2022). In vascular diseases, endothelial dysfunction is a systemic pathological state of the endothelium (the inner lining of blood vessels) and can be broadly defined as an imbalance between vasodilating and vasoconstricting substances produced by (or acting on) the endothelium. "IS activates the aryl hydrocarbon receptor (AhR) mediating oxidative stress and endothelial dysfunction via activation of the CYP1A1 pathway." (PMID 35202128, 2022). "Moreover, with higher doses of cystine we observed an increase in AhR expression and activation (CYP1A1) and there is strong evidence on the role of AhR activation by exogenous and endogenous metabolites in endothelial dysfunction in vitro and in vivo." (PMID 34573115, 2021).